MCM8 (minichromosome maintenance 8 homologous recombination repair factor)
Description:
Component of the MCM8-MCM9 complex, which is involved in the repair of double-stranded DNA breaks (DBSs) and DNA interstrand cross-links (ICLs) by homologous recombination (HR). The MCM8-MCM9 complex is a 3'-5' DNA helicase and single-stranded (ss)DNA-stimulated ATPase which binds ssDNA in the presence of nucleoside triphosphates. Required for DNA resection by the MRE11-RAD50-NBN/NBS1 (MRN) complex by recruiting the MRN complex to the repair site and by promoting the complex nuclease activity. Indirectly regulates the recruitment of downstream effector RAD51 to DNA damage sites including DBSs and ICLs, probably by regulating the localization of the MNR complex. The MCM8-MCM9 complex is dispensable for DNA replication and S phase progression. May play a non-essential for DNA replication: may be involved in the activation of the prereplicative complex (pre-RC) during G(1) phase by recruiting CDC6 to the origin recognition complex (ORC). Facilitates somatic mitochondrial (mt)DNA recombination. Plays a key role during gametogenesis, probably by regulating HR (By similarity). Stabilizes MCM9 protein.
Synonyms: C20orf154; MGC4816; MGC12866; MGC119522; MGC119523; dJ967N21.5; REC; POF10
Tractability: Small molecule: a structure with a bound ligand is known. PROTAC: ubiquitination databases record sites on it.
Gene: Protein-coding gene on chromosome 20 (5,949,767 to 5,998,977, forward strand). Ensembl gene ENSG00000125885.
Subcellular location: Nucleus; Chromosome; Cytoplasm; Mitochondrion matrix
Subcellular location (Human Protein Atlas): Nucleoplasm; Cytosol
Pathways (Reactome):
DNA Replication: Activation of the pre-replicative complex; CDC6 association with the ORC:origin complex; Orc1 removal from chromatin; Unwinding of DNA
Cell Cycle: Activation of ATR in response to replication stress; E2F-enabled inhibition of pre-replication complex formation
Gene Ontology:
Molecular function: 3'-5' DNA helicase activity; ATP hydrolysis activity; chromatin binding; enzyme binding; MutLbeta complex binding; MutSalpha complex binding; MutSbeta complex binding; protein binding; single-stranded DNA binding; single-stranded DNA helicase activity; ATP binding; DNA binding
Biological process: DNA damage response; DNA replication; double-strand break repair via homologous recombination; protein localization to chromatin; protein stabilization; recombinational interstrand cross-link repair; female gamete generation; male gamete generation; mismatch repair involved in maintenance of fidelity involved in DNA-dependent DNA replication
Cellular component: chromosome; cytoplasm; MCM8-MCM9 complex; mitochondrial matrix; nucleoplasm; nucleus; MCM complex
Genetic constraint (gnomAD): Loss-of-function variants: 65 observed, 82.37 expected, observed/expected ratio (o/e) 0.79, 90% interval 0.64 to 0.97. The upper end of that interval is the gene's LOEUF score, 0.97, which puts it in group 4 of 6, group 1 being the genes least tolerant of losing a copy. Missense variants: 854 observed, 942.77 expected, observed/expected ratio (o/e) 0.91, 90% interval 0.86 to 0.96. Synonymous variants: 326 observed, 324.89 expected, observed/expected ratio (o/e) 1, 90% interval 0.92 to 1.1.
Homologues: Orthologues: chimpanzee MCM8 (98% identical), macaque MCM8 (94% identical), rabbit MCM8 (92% identical), dog MCM8 (91% identical), guinea pig MCM8 (91% identical), pig MCM8 (91% identical), rat Mcm8 (89% identical), mouse Mcm8 (88% identical), tropical clawed frog mcm8 (73% identical), zebrafish mcm8 (70% identical), Drosophila melanogaster rec (27% identical). Paralogues in human: MCM9 (27% identical), MCM2 (26% identical), MCM4 (25% identical), MCM5 (22% identical), MCM6 (22% identical), MCM7 (22% identical), MCM3 (22% identical), MCMDC2 (14% identical).
Diseases named in the same sentence as MCM8 in open-access papers:
MCM8 is named in the same sentence as 68 diseases in open-access papers, as found by Europe PMC text mining. Sharing a sentence is not in itself a finding about the gene and the disease. The quoted sentences say what the papers report.
breast carcinoma (8 papers, 2017 to 2025). "A patient with breast cancer carried biallelic MCM8 genetic variants in the context of a breast cancer family, and 5 additional heterozygote carriers were detected." (PMID 32841224, 2020). "Single biallelic MCM9 variant carriers were diagnosed with gastric cancer (HP:0012126), a human papillomavirus-unrelated clear cell carcinoma of the cervix (HP:0031522), and melanoma (HP:0012056), whereas a biallelic MCM8 variant carrier was diagnosed with breast cancer (HP:0003002)." (PMID 40684266, 2025). "One male patient affected by Lynch syndrome with fertility problems and two patients affected by breast cancer were found to be carriers of biallelic MCM8 mutations, suggesting a role of this gene in the germline predisposition to breast cancer and hereditary colorectal cancer (CRC)." (PMID 34501457, 2021). "Besides, as highlighted by the biallelic MCM8 carrier with breast cancer, a potential pleiotropy effect for this gene could be hypothesized to include germline predisposition to breast cancer besides CRC." (PMID 32841224, 2020). "Two monoallelic MCM8 variant carriers were diagnosed with CRC, another two with polyposis, and two individuals with a monoallelic MCM8 variant were diagnosed with breast cancer." (PMID 40684266, 2025). "Among the 51 biallelic MCM8 variant carriers in the 100000 Genomes Project, 2 individuals (3.9%) had CRC, 3 (5.9%) had colonic polyps, 3 (5.9%) had colonic adenomas, 3 (5.9%) had rectal polyps, 2 (3.9%) had hypothyroidism, and 5 (9.8%) had breast cancer." (PMID 40684266, 2025).
gastric cancer (7 papers, 2020 to 2025). A primary or metastatic malignant neoplasm involving the stomach. "Biallelic MCM9 variants are associated with polyposis, gastric cancer, and early-onset colorectal cancer, while both biallelic MCM8 and MCM9 variants are linked to hypogonadism and the early development of germ cell tumors." (PMID 40684266, 2025). "MCM8 upregulation was related to advanced tumor grade and lymph node metastasis, and indicated poor prognosis in lung cancer, bladder cancer, as well as gastric cancer." (PMID 40095759, 2025). "Our data suggest that biallelic MCM9 variants are associated with polyposis, gastric cancer, and early-onset CRC, while both biallelic MCM8 and MCM9 variants are linked to hypogonadism and the early development of germ cell tumors." (PMID 40684266, 2025). "Collectively, our data indicate that biallelic MCM9 variants are associated with polyposis, gastric cancer, and early-onset CRC, while both biallelic MCM8 and MCM9 variants are linked to hypogonadism and the early development of germ cell tumors." (PMID 40684266, 2025). "MCM8 contributes to the progression of various cancers, such as cholangiocarcinoma, osteosarcoma, gastric cancer and glioma." (PMID 37349788, 2023). "Our analysis of the 100000 Genomes Project reveals that biallelic MCM9 variant carriers are at increased risk for polyposis and gastric cancer, a pattern not observed in biallelic MCM8 carriers." (PMID 40684266, 2025). "MCM8 is an oncogene and predicts poor prognosis in gastric cancer (GC) patients." (PMID 38988047, 2024). "The tumor promotor function of MCM8 in gastric cancer is realized by binding with RPS15A." (PMID 38988047, 2024). "MCM8 expression in gastric cancer tissues and para‐carcinoma tissues." (PMID 38988047, 2024). "However, research concerning the role of MCM8 itself in the development and progression of human cancers is still rarely reported, which is only observed in gastric cancer." (PMID 33828075, 2021). "hsa_circ_0005699 was previously reported to downregulate MCM8 and NCAPD2 expression by acting as a sponge of hsa-miR-504, functioning as tumor suppressor in gastric cancer." (PMID 33553144, 2020). "Likewise, in our case series, which included 26 MCM8 and 28 MCM9 variant carriers, we documented polyposis, gastric cancer, and early-onset colorectal cancer (CRC) in MCM9 carriers but not in MCM8 carriers." (PMID 40684266, 2025). "Meanwhile, there have been several articles reveal that MCM2 and MCM5 may serve as prognostic indicators of patients with gastric cancer, but there is no such article on MCM8." (PMID 33155430, 2020). "Moreover, there is no in vitro or in vivo study on the function of MCM8 in gastric cancer." (PMID 33155430, 2020). "However, there have been several articles reveal that MCM2 and MCM5 may serve as prognostic indicators of patients with gastric cancer, but there is no such article on MCM8." (PMID 33155430, 2020).
osteosarcoma (5 papers, 2021 to 2025). A usually aggressive malignant bone-forming mesenchymal neoplasm, predominantly affecting adolescents and young adults. "MCM8 is expressed at high levels in osteosarcoma tissues, and associated with more advanced tumour grade and pathological stage; silencing of MCM8 through regulating CTGF can suppress osteosarcoma progression." (PMID 39031896, 2024). "The analysis using clinical specimens as object showed the upregulation of MCM8 in osteosarcoma and its significant association with the malignant grade and pathological stage." (PMID 33828075, 2021). "In conclusion, the results of our study demonstrated that MCM8 is significantly associated with the promotion of cell proliferation and cell migration, and the inhibition of cell apoptosis in osteosarcoma, thus predicting more advanced tumor grade and pathological stage." (PMID 33828075, 2021). "The role of MCM8 in promoting various human cancer cell phenotypes has been highlighted in colorectal cancer and osteosarcoma." (PMID 40095759, 2025). "In this study, we found that MCM8 has significantly higher expression level in osteosarcoma tissues in comparison with normal tissues, which was also correlated with more advanced tumor grade and pathological stage." (PMID 33828075, 2021). "More importantly, upon CTGF knockdown, the MCM8-induced promotion of osteosarcoma development was significantly alleviated." (PMID 33828075, 2021). "As per the results presented so far, we indicated that MCM8 downregulation repressed proliferation, migration, and invasion but promoted apoptosis and cycle of osteosarcoma cells." (PMID 33828075, 2021). "Subsequent verification showed that CTGF exhibited a feature of coexpression with MCM8 in osteosarcoma tissues or cells." (PMID 33828075, 2021). "Herein, MCM8 was identified as a key participant in the development and progression of osteosarcoma." (PMID 33828075, 2021). "In agreement with the role of MCM proteins as indicators of cell proliferation, knockdown/overexpression of MCM8 inhibited/promoted osteosarcoma cell proliferation in vitro and tumor growth in vivo." (PMID 33828075, 2021). "Aiming to further explore the roles of MCM8 in osteosarcoma, MNNG/HOS cells were transfected with the lentivirus plasmids (shMCM8 or shCtrl)." (PMID 33828075, 2021). "We also use xenograft mice model to demonstrate the knockdown of MCM8 as a strategy to inhibit osteosarcoma development in vivo." (PMID 33828075, 2021). "With the objective of determining the roles of MCM8 in osteosarcoma, we evaluated the differential expression of MCM8 between normal and osteosarcoma tissues, and between stages of disease." (PMID 33828075, 2021). "Herein, MCM8/CTGF turned out to be a new path that CTGF executes its regulatory effects in osteosarcoma." (PMID 33828075, 2021). "Dual target of MCM8 and CTGF exhibited stronger inhibitory effects on osteosarcoma development than mere MCM8 knockdown." (PMID 33828075, 2021). "As presented above, these data suggested that MNNG/HOS cells with MCM8 depletion curbed osteosarcoma tumorigenesis as xenografts in nude mice." (PMID 33828075, 2021). "For performing experiments to study mechanism, we evaluated MCM8 levels in human osteoblast hFOB1.19 and a panel of osteosarcoma cell lines so as to find the most appropriate model (P < 0.001)." (PMID 33828075, 2021). "Bearing all these in mind, this study aims to clarify the expression characteristics of MCM8 in osteosarcoma and its role in tumor progression." (PMID 33828075, 2021). "After establishing a possible involvement of MCM8 in osteosarcoma in vitro, we turned to in vivo models for further verification." (PMID 33828075, 2021). "We were interested in finding downstream mechanism that was functionally involved in MCM8’s actions towards promoting osteosarcoma." (PMID 33828075, 2021).
osteosarcoma (continued). "Moreover, MCM8 has recently been identified as key regulator in the development and progression of several types of human cancers such as gastric cancer, osteosarcoma, bladder cancer, glioma and cholangiocarcinoma." (PMID 37710286, 2023). "In vitro and in vivo investigations suggested that MCM8 silencing could be an effective strategy to suppress the development and even the metastasis of osteosarcoma." (PMID 33828075, 2021). "Moreover, CTGF, whose effects of osteosarcoma have been reported to some extent, was revealed as a potential downstream target of MCM8." (PMID 33828075, 2021). "Herein, it was speculated that CTGF was the downstream target of MCM8 involved in the regulation of osteosarcoma." (PMID 33828075, 2021). "More importantly, mechanistic study identified CTGF as a potential downstream target of MCM8, silencing of which could enhance the regulatory effects of MCM8 knockdown and alleviate the effects of MCM8 overexpression on osteosarcoma development." (PMID 33828075, 2021). "In summary, MCM8/CTGF axis was revealed as critical participant in the development and progression of osteosarcoma and MCM8 may be a promising therapeutic target for osteosarcoma treatment." (PMID 33828075, 2021). "The Mann–Whitney U analysis of the correlation between tumor characteristics and MCM8 expression in clinical samples of osteosarcoma showed that MCM8 was positively correlated to age, pathological stage, and grade malignancy, which was further verified by the Pearson correlation analysis." (PMID 33828075, 2021). "Next, in an attempt to identify the synergistic function of CTGF and MCM8 in the development of osteosarcoma, MNNG/HOS cell models with mere CTGF depletion and concurrent MCM8 depletion and CTGF depletion were prepared, verified, and used in the following functional experiments." (PMID 33828075, 2021). "Based on the results that were presented, it was quite apparent that CTGF might be a target of MCM8 in the regulation of osteosarcoma." (PMID 33828075, 2021). "Knockdown of CTGF could deepen the regulatory effects of MCM8 silencing on osteosarcoma development." (PMID 33828075, 2021). "Further mechanistic study revealed that MCM8 may regulate a variety of apoptosis-related proteins and Akt pathway to influence osteosarcoma development." (PMID 33828075, 2021). "The following detection of cell phenotypes indicated not only that MCM8 overexpression promotes cell proliferation, colony formation, and cell migration as well as inhibits cell apoptosis but also that CTGF knockdown could partially reverse the MCM8-induced regulatory effects on osteosarcoma cells." (PMID 33828075, 2021). "In consistent with the role of MCM proteins as indicator of cell proliferation, we also found that knockdown of MCM8 could impede osteosarcoma cell proliferation, together with the promotion of cell apoptosis, arrest of cell cycle in G2 phase, and suppression of cell migration." (PMID 33828075, 2021). "We next examined whether MCM8 depletion altered the proliferation of osteosarcoma cell lines." (PMID 33828075, 2021). "Therefore, MCM8 may be considered as a novel therapeutic target of osteosarcoma." (PMID 33828075, 2021). "It was evident that MCM8 depletion in MNNG/HOS and U-2OS osteosarcoma cell lines significantly decreased cell proliferation (P < 0.001)." (PMID 33828075, 2021). "In this study, we found that osteosarcoma tissues possessed generally higher MCM8 expression than normal bone tissues." (PMID 33828075, 2021).
glioma (4 papers, 2022 to 2024). A benign or malignant brain and spinal cord tumor that arises from glial cells (astrocytes, oligodendrocytes, ependymal cells). "Abnormal upregulation of MCM8 expression is observed in glioma, and high expression of MCM8 is associated with poor prognosis." (PMID 37349788, 2023). "Further, MCM8 knockdown induces G0/G1 cell cycle arrest and apoptosis, as well as suppressing self‐renewal and proliferation of glioma stem cells (GSCs), while MCM8 knockdown improves GSC sensitivity to radiation and Temozolomide treatments." (PMID 39031896, 2024). "The roles and mechanisms of E2F4 and MCM8 in maintaining the characteristics of GSCs and regulating gliomas progression still needs to be further explored at the in vivo level." (PMID 37349788, 2023). "Overall, the expression of LIN9, MCM8, CEP72, POLA1, DBF4, NDE1 and CDKN2C increase the prognostic risk for patients with glioma." (PMID 37349788, 2023). "The findings presented herein indicated that E2F4 and MCM8 represent promising therapeutic targets for the treatment of gliomas." (PMID 37349788, 2023). "We utilized the cox proportional hazard model and found that macrophages, neutrophils, MCM8, and MCM9 expression were associated with a poor prognosis of glioma." (PMID 36465369, 2022). "Our analysis revealed a significant positive correlation between E2F4 and MCM8, POLA1, DBF4, NDE1 or CDKN2C expression in primary gliomas." (PMID 37349788, 2023). "In recurrent gliomas, E2F4 showed a significant positive correlation with the expression of MCM8, DBF4 and CDKN2C." (PMID 37349788, 2023). "The correlation between E2F4 and LIN9, MCM8, CEP72, POLA1, DBF4, NDE1 or CDKN2C expression in glioma tissues was analyzed using CGGA." (PMID 37349788, 2023). "The expression of MCM8, DBF4 and CDKN2C displayed a significant positive correlation with E2F4 expression in both primary and recurrent glioma tissues." (PMID 37349788, 2023). "There was a strong positive correlation between E2F4 expression and the expression of MCM8, DBF4 and CDKN2C in both primary and recurrent glioma tissues, with the most prominent impact on patient prognosis being observed for MCM8." (PMID 37349788, 2023). "Existing study suggested that MCM8 was regulated by EGFR signaling and interacted with DNA-replication-initiating factors to promote the growth of glioma stem cells." (PMID 36575045, 2022). "We utilized the cox proportional hazard model and found that macrophages, neutrophils, MCM8, and MCM9 expression were related to the poor prognosis of glioma patients." (PMID 36465369, 2022). "Furthermore, MCM5, MCM8, and MCM10 CNV affected the prognosis of glioma patients." (PMID 36465369, 2022). "Furthermore, MCM5, MCM8, and MCM10 CNV affect the prognosis of glioma patients." (PMID 36465369, 2022).
hepatocellular carcinoma (4 papers, 2022 to 2026). A malignant tumor that arises from hepatocytes. "However, findings suggest that in hepatocellular carcinoma (HCC) tissue samples with high MCM8 expression, a lower presence of activated NK cells was detected." (PMID 41139700, 2026).